TAS2R3 (taste 2 receptor member 3)
Description:
Gustducin-coupled receptor implicated in the perception of bitter compounds in the oral cavity and the gastrointestinal tract. Signals through PLCB2 and the calcium-regulated cation channel TRPM5.
Synonyms: T2R3
Tractability: Antibody: its Gene Ontology location is reachable by antibodies, with high confidence; UniProt predicts a signal peptide or a membrane-spanning region. PROTAC: a small molecule that binds it is known.
Target class: Membrane receptor; Taste receptor (taste family GPCR); Taste family G protein-coupled receptor
Gene: Protein-coding gene on chromosome 7 (141,764,097 to 141,765,197, forward strand). Ensembl gene ENSG00000127362.
Subcellular location: Membrane
Pathways (Reactome):
Signal Transduction: Class C/3 (Metabotropic glutamate/pheromone receptors); G alpha (i) signalling events
Sensory Perception: Sensory perception of sweet, bitter, and umami (glutamate) taste
Gene Ontology:
Molecular function: bitter taste receptor activity; taste receptor activity; G protein-coupled receptor activity
Biological process: detection of chemical stimulus involved in sensory perception of bitter taste; G protein-coupled receptor signaling pathway; sensory perception of taste
Cellular component: membrane; plasma membrane
Genetic constraint (gnomAD): Loss-of-function variants: 10 observed, 16.05 expected, observed/expected ratio (o/e) 0.62, 90% interval 0.38 to 1.06. The upper end of that interval is the gene's LOEUF score, 1.06, which puts it in group 4 of 6, group 1 being the genes least tolerant of losing a copy. Missense variants: 383 observed, 391.06 expected, observed/expected ratio (o/e) 0.98, 90% interval 0.9 to 1.07. Synonymous variants: 162 observed, 149.15 expected, observed/expected ratio (o/e) 1.09, 90% interval 0.95 to 1.24.
Homologues: Orthologues: chimpanzee TAS2R3 (99% identical), macaque TAS2R3 (93% identical), pig TAS2R3 (72% identical), dog TAS2R3 (70% identical), rabbit TAS2R3 (69% identical), guinea pig TAS2R3 (66% identical), rat Tas2r137 (64% identical), mouse Tas2r137 (64% identical). Paralogues in human: TAS2R7 (41% identical), TAS2R8 (38% identical), TAS2R10 (38% identical), TAS2R9 (37% identical), TAS2R42 (35% identical), TAS2R13 (33% identical), TAS2R43 (33% identical), TAS2R30 (33% identical), TAS2R38 (33% identical), TAS2R46 (33% identical), TAS2R14 (32% identical), TAS2R31 (32% identical), and 11 more.
Diseases named in the same sentence as TAS2R3 in open-access papers:
TAS2R3 is named in the same sentence as 9 diseases in open-access papers, as found by Europe PMC text mining. Sharing a sentence is not in itself a finding about the gene and the disease. The quoted sentences say what the papers report.
papillary thyroid carcinoma (4 papers, 2018 to 2021). "Recently, genetic variation in TAS2R3 has been associated with the risk of papillary thyroid carcinoma and regulates thyroid function." (PMID 32253825, 2020). "Taken together, genetic variations in TAS2R3/4 may contribute to alteration of the maturation and/or function of thyrocytes and the risk of developing papillary thyroid carcinoma." (PMID 34674725, 2021). "Intriguingly, several lines of evidence indicated that Korean females with TAS2R3/4 CC haplotype (rs2270009 and rs2234001, respectively) were at a lower risk of developing papillary thyroid carcinoma than those with the remaining haplotypes (OR = 0.59; 95% CI = 0.36–0.97)." (PMID 34674725, 2021).
dental caries (2 papers, 2021 to 2022). The decay of a tooth, in which it becomes softened, discolored, and/or porous. "This study also supported the role of taste receptor genes in dental caries (TAS2R38, TAS2R3, TAS2R4, TASR25), which have been associated with dental caries in previous studies." (PMID 34311721, 2021). "In summary, this study found multiple associations near genes that may play important roles in dental caries, such as TAS2R38, TAS2R3, TAS2R4, TASR25, DLX3 and DLX4, several of which have plausible biological functions relevant to tooth development and cariogenesis." (PMID 34311721, 2021). "An interesting suggestive association for the permanent dentition DFT was at 7q34 (lead SNP rs11197981; P = 1.11 × 10−6), approximately 200 kb downstream of taste receptor genes (TAS2R38, TAS2R3, TAS2R4, TASR25), which have plausible roles in dental caries." (PMID 34311721, 2021).
Polysyndactyly (2 papers, 2020 to 2024). Polysyndactyly or PPD4 is a form of preaxial polydactyly of fingers (see this term), a limb malformation syndrome, characterized by the presence of a thumb showing the mildest degree of duplication, being broad, bifid or with radially deviated distal phalanx. "In 2020, a report was published suggesting that frameshift mutations of GLI3, ANKUB1, and TAS2R3 might alter protein functions and accelerate the progression of polysyndactyly (PSD), an autosomal dominant genetic limb malformation." (PMID 38871700, 2024).
male infertility (1 paper, 2020). The inability of the male to effect fertilization of an ovum after a specified period of unprotected intercourse. "In addition, the SNP of TAS2R3 has been closely correlated to male infertility." (PMID 32253825, 2020).
ovarian carcinoma (1 paper, 2023). A malignant neoplasm originating from the surface ovarian epithelium. "Our study revealed that high expression of TAS2R10, TAS2R3, and TAS2R50 is significantly associated with poor prognosis in ovarian cancer, as demonstrated by our analysis of clinical samples." (PMID 37799274, 2023).
tumor (1 paper, 2023). "A significant increase in TAS2R10, TAS2R3, and TAS2R50 expression was observed in PNI-positive tumor tissue samples compared to PNI-negative." (PMID 37799274, 2023).
TAS2R3 also shares sentences with these, for which no sentence is quoted: cancer (1 paper); female infertility (1); papillary carcinoma (1).